KCTD2 (potassium channel tetramerization domain containing 2)
Synonyms: KIAA0176
Tractability: PROTAC: ubiquitination databases record sites on it.
Gene: Protein-coding gene on chromosome 17 (75,032,575 to 75,065,889, forward strand). Ensembl gene ENSG00000180901.
Gene Ontology:
Molecular function: protein binding; protein-containing complex binding; cullin family protein binding
Biological process: proteasome-mediated ubiquitin-dependent protein catabolic process; protein homooligomerization
Cellular component: Cul3-RING ubiquitin ligase complex; cytoplasm
Genetic constraint (gnomAD): Loss-of-function variants: 13 observed, 18.27 expected, observed/expected ratio (o/e) 0.71, 90% interval 0.46 to 1.13. The upper end of that interval is the gene's LOEUF score, 1.13, which puts it in group 4 of 6, group 1 being the genes least tolerant of losing a copy. Missense variants: 200 observed, 251.32 expected, observed/expected ratio (o/e) 0.8, 90% interval 0.71 to 0.89. Synonymous variants: 131 observed, 109.54 expected, observed/expected ratio (o/e) 1.2, 90% interval 1.04 to 1.38.
Homologues: Orthologues: chimpanzee KCTD2 (99% identical), macaque KCTD2 (98% identical), dog KCTD2 (98% identical), pig KCTD2 (98% identical), mouse Kctd2 (96% identical), rat Kctd2 (94% identical), guinea pig KCTD2 (90% identical), zebrafish kctd2 (76% identical), tropical clawed frog KCTD2 (75% identical), Drosophila melanogaster inc (44% identical), Caenorhabditis elegans inso-1 (43% identical). Paralogues in human: KCTD5 (66% identical), KCTD17 (56% identical), KCTD9 (34% identical).
Diseases named in the same sentence as KCTD2 in open-access papers:
KCTD2 is named in the same sentence as 12 diseases in open-access papers, as found by Europe PMC text mining. Sharing a sentence is not in itself a finding about the gene and the disease. The quoted sentences say what the papers report.
glioma (2 papers, 2021 to 2025). A benign or malignant brain and spinal cord tumor that arises from glial cells (astrocytes, oligodendrocytes, ependymal cells). "Moreover, our finding of decreased expression of KCTD2 and KCTD10 aligns with reports in glioma, where reduced levels of these genes were associated with tumor progression." (PMID 40832836, 2025). "Indeed, KCTD2 promotes ubiquitination and degradation of the oncogene c-Myc, and reduced KCTD2 mRNA levels are present in glioma cells, promoting tumor growth in vivo." (PMID 34001146, 2021).
age (1 paper, 2018). A temporal measurement of the time period elapsed since an identifiable point in the life cycle of an organism. "ATP5H is related to ATP synthase function, and the ATP5H/KCTD2 locus is associated with age-related Alzheimer’s disease risk." (PMID 29907735, 2018).
Alzheimer disease (1 paper, 2017). A progressive, neurodegenerative disease characterized by loss of function and death of nerve cells in several areas of the brain leading to loss of cognitive function such as memory and language. "Human mutations at the KCTD2/ATP5H locus are associated with Alzheimer’s disease, and mutations of KCTD17 with myoclonic dystonia." (PMID 28558011, 2017).
COVID-19 (1 paper, 2024). A disease caused by infection with severe acute respiratory syndrome coronavirus 2. "DAW1, ESF1, KCTD2, USP45, PNMA8A, SYNDIG1L, and CC2D2B are novel genes/proteins that may be linked to COVID-19." (PMID 38674024, 2024).
dementia (1 paper, 2021). Loss of intellectual abilities interfering with an individual's social and occupational functions. "The SNPs rs876461 (PRKD3; P = .02), rs117618017 (APH1B; P = .03), rs4844610 (CR1; P = .04), rs7584040 (BIN1; P = 2 × 10–3), rs11168036 (HBEGF; P = 8 × 10–3), rs143429938 (CLU/MIR6843; P = .04), and rs8064326 (KCTD2; P = 3 × 10‐4) were independently associated with incident dementia." (PMID 33532541, 2021).
ischemic stroke (1 paper, 2019). A stroke disorder caused by obstruction of blood flow to the brain, due to thrombotic (local blood clot formation) or embolic (due to a blood clot or other material traveling from another site) event. "Genome wide association studies identified KCTD2 as a shared susceptibility gene between AD and ischemic stroke." (PMID 31545826, 2019).
schizophrenia (1 paper, 2022). A major psychotic disorder characterized by abnormalities in the perception or expression of reality.
small vessel stroke (1 paper, 2016). "A meta‐analysis of AD IGAP and METASTROKE + small vessel stroke GWAS data highlighted a region (ATP5H/KCTD2/ICT1) associated with both diseases (p = 1.8 × 10−8)." (PMID 26913989, 2016). "The strongest association was with rs11870474 [ATP5H/KCTD2] for small vessel stroke (p = 0.0042)." (PMID 26913989, 2016).
cancer (2 papers, 2021 to 2025). A tumor composed of atypical neoplastic, often pleomorphic cells that invade other tissues. "Evidence of KCTD2 involvement in cancer derive from studies conducted on glioblastoma tumor cells and CRC cancer patients." (PMID 34001146, 2021). "However, the associations of KCTD2, KCTD15, and KCTD21 with cancer progression remain underexplored, making our findings novel and significant." (PMID 40832836, 2025). "KCTD2, -5, -9, -17 proteins belong to group E. For all these proteins, there is still little information and their role in physiological and pathological contexts and even less is known about their involvement in the onset or progression of cancer." (PMID 34001146, 2021). "Emerging evidence has highlighted the significance of various gene families in cancer progression, including the KCTD family, comprising genes, including KCTD2, KCTD5, KCTD9, KCTD10, KCTD12, KCTD15, KCTD16, and KCTD21." (PMID 40832836, 2025).
tumor (2 papers, 2021 to 2025). "The validation experiments conducted using the A2780 cell line further confirmed the tumor‐causing roles of KCTD2 and KCTD10 in OC." (PMID 40832836, 2025). "Conversely, KCTD2 has been linked to epigenetic regulation, including chromatin remodeling and transcriptional repression, which may contribute to tumor suppression in certain contexts." (PMID 40832836, 2025). "Notably, overexpression of KCTD2 and KCTD3 in breast cancer is associated with poor prognosis and aggressive tumor phenotypes, emphasizing their possible role in promoting tumor growth and metastasis." (PMID 40832836, 2025). "Given BRCA's significance in OC proliferation and therapeutic response, future research should investigate whether BRCA expression modulates the tumor‐suppressive effects of KCTD2 and KCTD10." (PMID 40832836, 2025). "Functional assays in SKOV3 and A2780 cells demonstrated that overexpression of KCTD2 and KCTD10 significantly inhibited cell proliferation, migration, and colony formation, suggesting their tumor‐suppressive roles." (PMID 40832836, 2025). "Additionally, we did not assess the potential correlation between KCTD2/KCTD10 and BRCA gene expression, which plays a crucial role in DNA repair and tumor progression in OC." (PMID 40832836, 2025).
KCTD2 also shares sentences with these, for which no sentence is quoted: lung carcinoma (1 paper); myoclonic dystonia (1).